EPAS1 (endothelial PAS domain protein 1)
Diseases named in the same sentence as EPAS1 in open-access papers (continued):
Sharing a sentence is not in itself a finding about the gene and the disease.
cancer (continued). "Interestingly, in non-cancer-affected controls, all gene-to-gene correlations were positive and strong in pre-menopausal cases and were either moderate for VEGFA and EPAS1 or not significant for other gene-to-gene correlations in post-menopausal." (PMID 39888575, 2026). "The ESCC cells with reduced EPAS1 expression (KYSE70−EPAS1 and KYSE150−EPAS1) cells showed significant (p < 0.01) reduction in wound healing, invasion, and migration capacity when compared with the control and nontransfected wild-type cancer cells." (PMID 33042797, 2020).
infection (30 papers, 2013 to 2025). The state of being infected such as from the introduction of a foreign agent such as serum, vaccine, antigenic substance or organism. "However, unlike HIF-1α protein levels, which were markedly elevated in FLS under hypoxic conditions, HIF-2α protein showed only minimal accumulation under the same conditions; however, Ad-Epas1 infection under normoxic conditions caused marked expression of HIF-2α protein." (PMID 24914685, 2014). "Moreover, overexpression of HIF-2α in precursor cells by Ad-Epas1 infection enhanced osteoclastogenesis." (PMID 24914685, 2014). "rs72773986 is an infection eQTL and a GTEx eQTL for ERAP2, and is predicted to alter binding of EPAS1, a key transcription factor for response to hypoxia." (PMID 34570765, 2021). "As similar to primary infection model, significant transcriptional activation of EPAS1, but not Hif1α, was observed in both LCLs." (PMID 38530845, 2024).
cardiovascular disease (6 papers, 2017 to 2024). "This article exhibited a comprehensive summary of EPAS1 including the molecular structure, biological function and regulatory network in PH and other relevant cardiovascular diseases, and furthermore, provided theoretical reference for the potential novel target for future PH intervention." (PMID 36923253, 2023).
Heart Disease (3 papers, 2020 to 2025). "Altogether, EPAS1 and BNIP3L are induced in ACM and DCM hearts, underscoring the relevance of these components in cardiac disease." (PMID 40034852, 2025).
hematological malignancies (3 papers, 2020 to 2023). "Although little is known about the regulatory mechanism between EPAS1 and PI3K/AKT signaling pathway in hematological malignancies, we can gain information and inspiration from these similar studies in solid tumors." (PMID 37124944, 2023).
EPAS1 also shares sentences with these, for which no sentence is quoted: osteosarcoma (22 papers); Insulin resistance (17); liver cancer (14); renal fibrosis (14); somatostatinoma (13); hemangioblastoma (12); kidney disease (11); metabolic disease (11); pancreatic ductal adenocarcinoma (11); brain tumor (10); chronic kidney disease (10); head and neck cancer (10); pancreatic neuroendocrine tumor (10); ischemia (8); myocardial ischemia (8); Chuvash polycythemia (6); endothelial dysfunction (6); lymphoma (6); Renal cyst (6); Stroke (6); thyroid cancer (6); chronic obstructive pulmonary disease (5); cyst (5); diabetic nephropathy (5); fibrosis (5); head and neck squamous cell carcinoma (5); heart failure (5); hemangioma (5); inflammation (5); ischemic stroke (5).
A further 271 diseases each share a sentence with EPAS1 in 5 papers or fewer.